TUSC3 (tumor suppressor candidate 3)
Diseases named in the same sentence as TUSC3 in open-access papers (continued):
Sharing a sentence is not in itself a finding about the gene and the disease.
cancer (33 papers, 2008 to 2025). A tumor composed of atypical neoplastic, often pleomorphic cells that invade other tissues. "The decreased expression of tumour suppressor candidate 3 (TUSC3) is associated with proliferation in several types of cancer, leading to an unfavourable prognosis." (PMID 35137520, 2022). "The SNVs with G:C to T:A transversion- or G:C to A:T transition-containing genes included cancer-associated genes such as Tgfbr2 and Tusc3." (PMID 34912374, 2021). "TUSC3 was initially identified as a homozygous deleted gene in metastasized prostate cancer patients and its deficiency upregulated cancer progression and tumorigenesis in ovarian, prostate, glioblastoma and pancreatic cancers." (PMID 30504895, 2018). "hsa-mir-190b is predicted to target TUSC3 by sequence matching, and both the miRNA and gene are implicated in cancer in the literature." (PMID 30557297, 2018). "Loss or downregulation of TUSC3 has been found in other cancers, such as of the colon, where its promoter becomes increasingly methylated with age in the healthy mucosa." (PMID 23046790, 2012). "However, various mutations were detected in other genes such as Tusc3 and Tgfbr2, which have been reported as cancer-associated or homeostatic squamous cell genes." (PMID 34912374, 2021). "However, it has been also reported that TUSC3 was associated with genetic amplification or enhanced cancer progression in head and neck cancer and colorectal cancer." (PMID 30504895, 2018). "Moreover, TUSC3 specifically enhanced the efficiency of N-linked glycosylation on integrin β1 and lectin protein family, which enhanced cancer progression in ovarian and prostate cancers." (PMID 30504895, 2018). "Moreover, TUSC3 downmodulation was associated with poor cancer survival rate (n = 223), suggesting that TUSC3 could play an important role in NSCLC metastasis." (PMID 30504895, 2018). "We observed that four subunits of OST showed a coordinated reduction in the inclusion of TRD from pre- to post-natal stages, which increased again in cancer patients in brain, with TUSC3 and RPN2 undergoing greatest change." (PMID 36509773, 2022). "On the basis of TCGA database, we found that TUSC3 exhibited different expression patterns in different cancers." (PMID 33976749, 2021). "For example, promoter CpG island hypermethylation-associated silencing of some genes, such as TUSC3 (tumor suppressor candidate 3) and POMT1 (protein O-mannosyltransferase 1), reduce circRNA production in cancer." (PMID 30774645, 2019). "From orthotopic xenograft studies, we confirmed the role of TUSC3 downregulation in promoting cancer metastasis." (PMID 30504895, 2018). "The Tumor Suppressor Candidate 3 (TUSC3) at chromosome 8p22 known to be frequently deleted in cancer is often found to be deleted in advanced stage of solid tumors." (PMID 30504895, 2018). "In this study, we summarize the advances in the studies of TUSC3 and comment on the potential roles of TUSC3 in diagnosis and treatment of TUSC3‐related diseases, especially cancer." (PMID 28272772, 2017). "In keeping with this line, high levels of TUSC3 protein were detected in adjacent normal tissue samples but were very low in cancer biopsies." (PMID 28288641, 2017). "The tumor suppressor candidate-3 (TUSC3/N33) locates to a genomic region frequently deleted or silenced in cancers." (PMID 29156678, 2017). "In this review, we focus on recent results related to TUSC3's role in varied diseases and discuss the potential applications of TUSC3 in ‘TUSC3‐related diseases’, especially in cancers." (PMID 28272772, 2017). "Upon silencing of TUSC3 in cancer cells, this fine-tuned regulation at the plasma membrane is impaired." (PMID 29156678, 2017). "A significant downregulation of TUSC3 expression was observed in more advanced stage cancer samples (P = 0.038)." (PMID 29088772, 2017).
cancer (continued). "Other genes of interest among these 15 include Tusc3, a candidate tumor suppressor gene, and Nek8, which plays a role in cell cycle progression and has been reported to affect cancer progression." (PMID 40112176, 2025). "However, TUSC3 gene, present at chromosome 8, shows its candidature in the development of different cancers such as ovarian, colorectal, pancreatic, prostate, esophageal and pharyngeal cancers." (PMID 38992585, 2024). "TUSC3 has been reported to be downregulated in several cancers, including GBM." (PMID 37894860, 2023). "Notably, the role of TUSC3 was examined in specific cancer subgroups based on their FIGO stage and the prognostic potential of the downregulation of its expression was investigated in FIGO I stage subjects." (PMID 35137520, 2022). "Therefore, it has been suggested that TUSC3 plays intricate and important roles in different types of cancer." (PMID 35137520, 2022). "Moreover, the knockdown of TUSC3 promoted migration and invasion of cancer cells, while the increased expression of TUSC3 exhibited the opposite effects." (PMID 35137520, 2022). "In addition, the role of TUSC3 in regulating cancer progression varies according to cancer types, but its role in regulating GC progression has not been reported." (PMID 34381729, 2021). "find that TUSC3 promotes cancer development in colorectal cancer." (PMID 34381729, 2021). "The roles of TUSC3 in cancer progression showed context-dependent manner in several solid tumors." (PMID 30504895, 2018). "To analyze whether HRD1-dependent ATF6α activation could mediate the role of TUSC3 in cancer metastasis, we performed a series of rescue experiments." (PMID 30504895, 2018). "The precise molecular mechanism through which TUSC3 is involved in the development of cancer remains unclear." (PMID 28272772, 2017). "This indicates that TUSC3 is correlated with cancer stage and invasive potential to some extent." (PMID 28272772, 2017). "Accumulated data have established a strong link between TUSC3 and cancer." (PMID 28272772, 2017). "This mode of TUSC3 expression silencing is a frequent occurrence in cancer cells." (PMID 28272772, 2017). "We also found that TUSC3 expression could be induced by 1,25-VD, and its expression was down-regulated in advanced stage cancer." (PMID 29088772, 2017). "Given NF-κB’s involvement in cancer and TUSC3’s involvement in N-glycosylation, the possible reverse correlation between TUSC3 and NF-κB may bridge NF-κB and N-glycosylation in cancer pathogenesis, which warrants further study." (PMID 26871953, 2016). "Thus, the role of TUSC3 is quite significant in the progression of many cancers." (PMID 38992585, 2024). "According to a recent study, the downregulation of TUSC3 expression may lead to lymph node or distant metastasis formation in a variety of cancer types, suggesting that the induction of cancer cell migration and invasion by TUSC3 may be the underlying pathogenic mechanism." (PMID 35137520, 2022). "Given that MGMT is not a known repressor of gene expression, it is possible that the suppression of TUSC3 promoter activation in MGMT-UM GSCs occurs through a complex or machinery mediated by MGMT, which suggests a novel role of MGMT in cancers." (PMID 37894860, 2023). "TUSC3 and ATRNL1 were predominantly methylated in cancer cell lines derived from the digestive system, such as stomach, pancreas and biliary tract, although their hypermethylation was also very common in hematological malignancies." (PMID 30018746, 2018). "This chromosomic region harbours the CSMD1, AGPAT5, TUSC3, DLC1, CLDN23, and MFHAS1 cancer-related genes." (PMID 30185896, 2018). "In the next step, we processed blood samples from 36 cancer patients and 12 healthy donors (cohort 1) using protocol A and measured the gene expression levels of EpCAM, MAL2, PPIC, and TUSC3 in the enriched cell fractions." (PMID 29416657, 2018).
cancer (continued). "Low amount of endogenous TUSC3 protein was expressed in HCT116 cells, while it was undetectable in the other cell lines tested including the non-cancer cell line HEK293T." (PMID 29156678, 2017). "Taken together, these data indicated that TUSC3 inhibits EGFR phosphorylation and down-stream signaling in human CRC and non-cancer cells." (PMID 29156678, 2017). "Interestingly, IHC results also showed that TUSC3 was overexpressed in other stromal cells regardless of the expression of TUSC3 protein in cancer cells, suggesting that the TUSC3-dependent metastatic regulation could be a cell autonomous effect." (PMID 30504895, 2018). "CTNNA3 and TUSC3, which have also been cited as candidate TSGs for the same reason, could also have their status as TSG re-evaluated in light of our results, given that for each of these genes we have identified a number of cancer-free adult individuals with exon-disrupting deletions." (PMID 20195527, 2010). "The occurrence of TUSC3, ATRNL1, POMT1 or SAMD4A promoter CpG island hypermethylation was not a restricted in vitro phenomenon of long-cultured cancer cell lines." (PMID 30018746, 2018).
neurodevelopmental disorder (2 papers, 2019 to 2024). A behavioral and cognitive disorder with onset during the developmental period that involves impaired or aberrant development of intellectual, motor, or social functions. "Furthermore, the deletion detected in the 8p23.3 region, affecting the TUSC3 gene which has been associated with a severe neurodevelopmental disorder, produced no detectable variation in the PS1-LMNB1_GFP hiPSCs’ characteristics." (PMID 38534351, 2024).
infection (1 paper, 2017). The state of being infected such as from the introduction of a foreign agent such as serum, vaccine, antigenic substance or organism. "Western blot analysis determined the increased expression of TUSC3 protein in the GBM cells after infection." (PMID 28303930, 2017). "To further evaluate the contribution of TUSC3 to the biological effects of miR-UL112-3p, we restored TUSC3 expression in GBM cells by infection with TUSC3 adenovirus (lacking the potential binding site of miR-UL112-3p)." (PMID 28303930, 2017).
TUSC3 also shares sentences with these, for which no sentence is quoted: cognitive defects (2 papers); head and neck squamous cell carcinoma (2); melanoma (2); pharynx carcinoma (2); small cell lung carcinoma (2); adenocarcinoma (1); autism (1); colon adenocarcinoma (1); colorectal adenocarcinoma (1); developmental delay (1); epilepsy (1); Esophageal Carcinoma (1); frontotemporal dementia (1); hematological malignancies (1); Miscarriage (1); oral submucous fibrosis (1); osteosarcoma (1); papillary thyroid cancer (1); Parkinson disease (1); pregnancy disorder (1); rectal cancer (1); rectum adenocarcinoma (1); schizophrenia (1); thyroid tumor (1); ulcerative colitis (1).